ENSG00000281383 (novel transcript, similar to YY1 associated myogenesis RNA 1 YAM1)
Gene: Long non-coding RNA gene on chromosome 21 (8,254,592 to 8,255,514, reverse strand). Ensembl gene ENSG00000281383.
Gene Ontology:
Molecular function: structural constituent of ribosome
Cellular component: ribosome